IKZF3 (IKAROS family zinc finger 3)
Diseases named in the same sentence as IKZF3 in open-access papers (continued):
Sharing a sentence is not in itself a finding about the gene and the disease.
asthma (26 papers, 2011 to 2025). "In the STEPS study, asthma risk alleles in IKZF3, GSDMA, GSDMB, ZPBP2, and ORMDL3 genes were associated with a higher risk of a wheezing illness (all P values ≤.02)." (PMID 36967681, 2023). "In the meta‐analysis of GWAS of asthma in Puerto Ricans (children and adults), the only locus that achieved genome‐wide significance for asthma risk was IKZF3, (rs907092) at chromosome 17q21." (PMID 33133517, 2020). "Finally, we leveraged bulk RNAseq in the CB of the VDAART trial to show that an interaction for vitamin D level and IKZF3 expression that was associated with reduced asthma risk at 3 years of age." (PMID 38567749, 2024). "Moreover, IKZF3 is also associated with numerous other diseases including asthma and hay fever, rheumatoid arthritis, inflammatory bowel disease and Crohn’s disease." (PMID 26331722, 2015). "To validate whether ORMDL3 is a risk factor for adult-onset asthma, we sought to replicate the association of polymorphisms in ORMDL3, GSDMB, ZPBP2 and IKZF3 and asthma in an adult Chinese Han population." (PMID 21985515, 2011). "Carrying 1 or 2 risk alleles for SNPs rs9303277 (IKZF3) and rs61816764 (FLG) was associated with childhood onset asthma and met statistical significance after Bonferroni correction." (PMID 40105091, 2025). "For instance, an ALL risk allele on IKZF3 (rs2290400(T)) appears to be protective against T1DM and asthma, whereas the risk allele for T1DM and asthma in the same gene is associated with a decreased risk of childhood ALL." (PMID 40392825, 2025). "Another interesting example is the IKZF3/GSDMB/ORMDL3 GWAS locus, which is linked to many autoimmune diseases, including RA, asthma, systemic sclerosis (SSc), and others." (PMID 39930543, 2025). "Among the protein-coding genes causally associated with unspecified asthma in lung and blood, seven are within the 17q12-21 locus (i.e., PGAP3, IKZF3, GSDMB, ORMDL3, GSDMA, MED24, and CASC3)." (PMID 39628479, 2024). "Mutations in these genes, including ORMDL3, GSDMB, ZPBP2, and IKZF3, result in reduced protein folding in the endoplasmic reticulum leading to an overall pro-inflammatory effect in asthma patients." (PMID 39237910, 2024). "Asthma risk alleles in GSDMA, GSDMB, IKZF3, ZPBP2, and ORMDL3 genes were associated with wheezing illnesses in early childhood, especially rhinovirus-positive wheezing illnesses." (PMID 36967681, 2023). "These were in loci previously associated with asthma exacerbations (GSDMB, RAD50, HLA‐DQB1, ADAM33, VDR, and CDHR3) or moderate‐to‐severe asthma (IKZF3, TSLP, MUC5AC, C11orf30, SMAD3, and WDR36)." (PMID 35754128, 2022). "Chromosome 17q21 is an area of interest for asthma and contains a cluster of genes linked to asthma in several GWAS studies, including the GSDMB (Gasdermin B) and IKZF3 (Ikaros family zinc finger protein 3) genes." (PMID 33133517, 2020). "Furthermore, signals rs9303277 (IKZF3) and rs61816764 (FLG) showed the strongest effect size with age of onset when carrying both risk alleles for moderate‐severe asthma compared with all the genetic signals and clinical features." (PMID 40105091, 2025). "We also found our genetic data replicated previous associations with childhood onset suggesting signals at the FLG and IKZF3 loci may drive childhood asthma." (PMID 40105091, 2025). "This genomic region consists of a number of genes, including ORMDL3, GSDMB, IKZF3, ZPBP2, and GSDMA that are in LD and may either be individually or jointly responsible for the asthma association." (PMID 30541564, 2018). "The distal IKZF3 intergenic region overlaps ncSNP (rs12946510) and similar to the ORMDL3 intronic enhancer, this region showed increased activity (H3K27ac enrichment) in subjects carrying the asthma-risk allele." (PMID 27848966, 2016). "Signals around the IKZF3 gene have also previously been reported in childhood age of onset GWAS studies suggesting that these signals may drive childhood onset of asthma." (PMID 40105091, 2025).
asthma (continued). "It is important to note, however, that while the current experimental evidence excludes IKZF3 (IKZF3 is not affected by the haplotype effect in LCLs or T lymphocytes), it is not sufficient for ruling out ZPBP2, GSDMB or GSDMA as contributors to predisposition to asthma." (PMID 22271045, 2012).
autoimmune disease (9 papers, 2018 to 2025). A disorder resulting from loss of function or tissue destruction of an organ or multiple organs, arising from humoral or cellular immune responses of the individual to their own tissue constituents. "and revealed the significant association of the T allele at IKZF3 rs907091 with susceptibility to autoimmune disease." (PMID 38193570, 2024). "Genome-wide association studies have shown that particular single nucleotide polymorphisms in IKZF3 are associated with autoimmune diseases, suggesting that normal AIOLOS function is essential to maintain immune homeostasis." (PMID 34694366, 2021). "IKZF3 (Aiolos) and IKZF2 (Helios), and BACH2 have been implicated in other autoimmune disease such as systemic lupus erythematosus (SLE) and Rheumatoid Arthritis (RA)." (PMID 36284352, 2022). "Additionally, overexpressed genes such as IKAROS family zinc finger 3 (IKZF3), MER proto-oncogene, tyrosine kinase (MERTK), and Fc receptor-like 5 (FCRL5) all have risk alleles associated with MS or other autoimmune diseases." (PMID 39596026, 2024). "Furthermore, IKZF3 (Aiolos) and IKZF2 (Helios), and BACH2 have been implicated in other autoimmune diseases such as systemic lupus erythematosus (SLE) and Rheumatoid Arthritis (RA)." (PMID 36284352, 2022). "The constructed gene networks revealed among the exome genes, partners previously implicated in autoimmune diseases, including the SLE-associated genes IKZF1, IKZF3, and ITGAX25,50,51, further supporting a role for the genes identified in the disease pathogenic pathways." (PMID 29884787, 2018).
breast carcinoma (8 papers, 2006 to 2025). "For instance, IKZF3 and STAT5A overlap in immune-related pathways, while FOXP4 exhibits some distinct enrichment patterns associated with breast cancer, suggesting potential cooperative and specialized regulatory mechanisms." (PMID 40923764, 2025). "Additionally we observed one mutation in IKZF3 (found also as often occuring in HER2+ cancers, as in our cohort) and in POLQ associated with poor prognoses in breast cancer patients." (PMID 41256402, 2025). "These three TFs play important roles in breast cancer development and progression: CUX1 is associated with poor prognosis in ER-positive breast cancer, NR4A1 promotes tumor cell metastasis, and IKZF3 is linked to poor prognosis in HER2+ and regulates cell proliferation." (PMID 40923764, 2025). "Interestingly, our preliminary analysis of clinical breast cancers shows that IKZF3 is overexpressed in a small subset of both HER2-positive as well as HER2-negative cancers, suggesting its expression may be elevated independent of ERBB2 amplification." (PMID 21247443, 2011). "Additionally, our study demonstrated that knocking down IKZF3 in HER2-specific chimeric antigen receptor T cells, which target breast cancer cells, resulted in the enhanced killing of cancer cells in both in vitro and xenograft models." (PMID 37904416, 2023).
chronic lymphocytic leukemia (8 papers, 2019 to 2024). "A recurring mutation in IKZF3 is identified as a potential cancer driver in chronic lymphocytic leukemia (CLL)." (PMID 39759140, 2024). "IKZF3 was recognized as a chronic lymphocytic leukemia driver gene associated with chromatin modification." (PMID 34844217, 2021). "Here we describe a novel combined immunodeficiency due to an IKZF3 mutation in a family presenting with T and B cell involvement, Pneumocystis jirovecii pneumonia, and/or chronic lymphocytic leukemia." (PMID 34694366, 2021). "Diseases associated with IKZF3 include Immunodeficiency 84 and Chronic Lymphocytic Leukemia." (PMID 36284352, 2022). "have shown that the overexpression of IKZF3 is a driver of BTK inhibitor resistance in chronic lymphocytic leukemia (CLL)." (PMID 36536188, 2022). "Gene IKZF3, which also exhibits a correlation with rs12936231, has been related to B cell chronic lymphocytic leukemia." (PMID 31362752, 2019).
systemic lupus erythematosus (8 papers, 2014 to 2026). An autoimmune multi-organ disease typically associated with vasculopathy and autoantibody production. "In Mendelian randomization, the blood expression of IKZF3 was positively associated with the risk of systemic lupus erythematosus (beta=0.41, SE=0.05, PIVW= 1.01E − 16)." (PMID 37019979, 2023). "It has been reported that IKAROS family of zinc finger 3 (IKZF3)-deficient mice spontaneously develop human systemic lupus erythematosus (SLE)-like phenotypes and produce anti-dsDNA Ab leading to immune complex-mediated glomerulonephritis." (PMID 25271777, 2014). "Among them, we identified pathogenic or likely pathogenic variants in genes previously associated with monogenic lupus, including a novel C1QA variant as well as other lupus-associated genes (COPA, ADAR, TLR7, IKZF3, RELA, PTPN11, SERPING1)." (PMID 41930824, 2026). "For instance, IKZF3, which was mapped by CHA enhancers, is a strong causal candidate for systemic lupus erythematosus as shown by Mendelian randomization." (PMID 37019979, 2023). "Expression of IKZF3 is largely restricted to T and B cells and the Aiolos knockout mouse, which spontaneously develops a lupus-like phenotype, is characterized by the chronic activation of B cells with increased levels of autoantibodies and glomerulonephritis." (PMID 33182226, 2020). "Three members, IKZF1 (IKAROS) (rs2366293-C, rs4917014-T), IKZF3 (AIOLOS) (rs2941509-T), and IKZF2 (HELIOS) (rs6435760-C) have been implicated in systemic lupus erythematosus (SLE)." (PMID 38885295, 2024). "This study aimed to assess the association between 14 single nucleotide polymorphisms (SNPs) in six genes (IRF8, TMEM39A, IKZF3, ORMDL3, GSDMB, and ZPBP2) and systemic lupus erythematosus (SLE) in a Chinese Han population sample." (PMID 28427360, 2017).
lymphoma (7 papers, 2014 to 2025). A malignant (clonal) proliferation of B- lymphocytes or T- lymphocytes which involves the lymph nodes, bone marrow and/or extranodal sites. "Furthermore, our observation that selected GATA-3 target genes, including c-Myc, CCR4, IKZF3 and ITK, are therapeutically targetable is noteworthy, as improved therapeutic strategies for these lymphomas are clearly needed." (PMID 36329027, 2022). "Multiple factors, such as EZH2, c-MYC, IKZF1, IKZF3, IRF4, and CDK6, which are essential for the proliferation and survival of malignant plasma cells and lymphoma, were decreased upon treatment with PM in all tested MM and lymphoma cell lines, including MM1S, MM1R, and TMD-8." (PMID 40562746, 2025).
Immunodeficiency (6 papers, 2014 to 2026). Failure of the immune system to protect the body adequately from infection, due to the absence or insufficiency of some component process or substance. "Posthumous genetic analysis found a heterozygous missense mutation in IKZF3, a gene where haploinsufficiency is linked to immunodeficiency and immune dysregulation." (PMID 41746515, 2026).
leukemia (6 papers, 2018 to 2024). A malignant (clonal) hematologic disorder, involving hematopoietic stem cells and characterized by the presence of primitive or atypical myeloid or lymphoid cells in the bone marrow and the blood. "This is partly due to their association with inborn errors of the immune system, thrombocytopenia, and/or predisposition to leukaemia (IKZF1 and IKZF3) and to somatic defects that are frequently occurring in haematological malignancies (IKZF1 and IKZF2)." (PMID 39406892, 2024). "miR-494-3p was mainly paired with immune genes (CD3G, CXCL13, CXCR5, KLRC4), some of which had been annotated as oncogenes in leukemia including IGF1 (DRG; pan-cancer), IKZF3 (driver; leukemia), NABP1 (oncogene; leukemia), and PDGFRA (oncogene; pan-cancer)." (PMID 32605588, 2020). "Selected dicarboximides displayed immunomodulatory activity and downregulated IKZF1 and IKZF3 transcription factors in K562 and MOLT-4 leukemia cells." (PMID 31487824, 2019). "Indeed, incubation of leukemia cells with the test dicarboximides resulted in downregulation of transcription factors IKZF1 and IKZF3, which are particularly important for development of T- and B-lymphocytes." (PMID 31487824, 2019).
acute lymphoblastic leukemia (5 papers, 2015 to 2023). Leukemia with an acute onset, characterized by the presence of lymphoblasts in the bone marrow and the peripheral blood. "Genetic data has revealed that the loss of IKZF1 and IKZF3 results in a block of lymphoid lineage differentiation and a susceptibility to develop acute lymphoblastic leukemia (ALL)." (PMID 30760870, 2019). "Then, IKZF3 was a frequently mutated tumor suppressor gene in acute lymphoblastic leukemia (ALL), and its deletion could block lymphocytic lineage differentiation and increase the susceptibility to developing ALL." (PMID 36755810, 2023). "Deletion of IKZF1 and IKZF3 is observed in patients with B-progenitor acute lymphoblastic leukemia (ALL), indicating a tumor suppressor function of the Ikaros family." (PMID 34680233, 2021).
Autoimmunity (5 papers, 2018 to 2025). The occurrence of an immune reaction against the organism's own cells or tissues. "Vitamin D induced the expression of the Ikzf3-encoded protein Aiolos to suppress IL-2 signaling and ameliorate cytokine production in Th2 cells thus demonstrating a mechanism for how vitamin D influences autoimmunity." (PMID 38567749, 2024). "IKZF3 is a transcription factor important for B-cell activation, and the lack of this gene causes a lupus like syndrome in mice, suggesting a role for the regulatory loop of IKZF3 and miR-326 in autoimmunity." (PMID 30622533, 2018). "Loss of IKZF3 in mice can prevent autoreactive B cells and decrease peritoneal, marginal and recirculating B cells, suggesting that low expression of IKZF3 could limit autoimmunity." (PMID 29755505, 2018). "Notably, IKZF3 and AFF3, transcriptional regulators of lymphocyte differentiation, have been recognized in European and Middle Eastern cohorts, reinforcing their cross-population relevance to autoimmunity and fibrosis." (PMID 41283471, 2025).
Crohn disease (5 papers, 2014 to 2023). A gastrointestinal disorder characterized by chronic inflammation involving all layers of the intestinal wall, noncaseating granulomas affecting the intestinal wall and regional lymph nodes, and transmural fibrosis. "IKZF3 is a transcription factor located within a T1D susceptibility locus at 17q12 and overlaps susceptibility loci for ulcerative colitis, Crohn’s disease, primary billiary cirrhosis and rheumatoid arthritis." (PMID 25170024, 2014).
lung carcinoma (5 papers, 2021 to 2024). "It was observed that these lung cancer cells gained this ability via the upregulation of the lymphocyte-restricted transcription factor and chromatin regulator Aiolos (gene IKZF3)." (PMID 39560993, 2024). "We observed positive correlations between three types of NLS and T-cell receptor-associated gene expression signatures, such as CD8A, CD3G, CCL5, TIGT, LCK and IKZF3 in lung cancers and primary melanomas after adjusting clinical factors." (PMID 37100920, 2023). "In lung cancer, overexpressed IKZF3 upregulates the expression of TWIST and matrix metalloproteinase-16, which promotes the epithelial-mesenchymal-transition and the transformation of cancer stem cells and leads to poor prognosis." (PMID 36353107, 2022).
melanoma (5 papers, 2020 to 2023). A malignant, usually aggressive tumor composed of atypical, neoplastic melanocytes. "While IKZF3 is associated with a higher risk in the TCGA melanoma cohort, it also correlates with treatment response in MEL_PROG and VALID_PROG." (PMID 35743743, 2022). "Although the roles of other Ikaros family members such as IKZF4–5 in melanoma remain unclear, IKZF3 may serve as biomarkers for the outcomes of treatments for SKCM that achieve a positive clinical prognosis." (PMID 36353107, 2022). "IKZF3 may therefore serve as potential targets for immunotherapy of melanoma." (PMID 36353107, 2022). "Together, these results indicate that highly expressed IKZF1–3 gain clinical significance for predicting the prognosis of patients with SKCM, IKZF3 is an independent prognostic factor of SKCM, thus suggesting that IKZF3 are prognostic biomarkers and immunotherapeutic targets of melanoma." (PMID 36353107, 2022).
primary biliary cirrhosis (5 papers, 2015 to 2020). "The IKZF3 synonymous SNP rs907092 (MAF = 0.30) had been associated with primary biliary cirrhosis, and CRCP SNP rs875971 (MAF = 0.47, located in 3′ UTR) with aortic root diameter alternations." (PMID 26331722, 2015).
rheumatoid arthritis (5 papers, 2014 to 2024). A chronic, systemic autoimmune disorder characterized by inflammation in the synovial membranes and articular surfaces. "Among the modules enriched for genes down-regulated with AD, M123, and its child module M444, anchored by ITK/IKZF3/ETS1, are significantly enriched for MS and rheumatoid arthritis etiologic genes, and, correspondingly, the modules are strongly enriched for a variety of immune functions." (PMID 38343831, 2024).
multiple sclerosis (4 papers, 2015 to 2018). A progressive autoimmune disorder affecting the central nervous system resulting in demyelination. "Our data indicate a possible regulatory role for the multiple sclerosis-associated IKZF3 and IQGAP1 variants." (PMID 27080863, 2016). "Using multiple sclerosis patients and healthy controls heterozygous for rs907091 and rs11609, we showed that the multiple sclerosis risk alleles at IKZF3 and IQGAP1 are expressed at higher levels as compared to the protective allele." (PMID 27080863, 2016). "For example, we predict a 76-nt driver element overlapping rs12946510 in the IKZF3 locus associated with multiple sclerosis in a tiled region of 3 kb, suggesting this may be the causal variant." (PMID 30568279, 2018). "We suggest that such cis-acting mechanisms may contribute to the multiple sclerosis association of single nucleotide polymorphisms at IKZF3 and IQGAP1." (PMID 27080863, 2016). "Consistent allelic imbalance was observed for rs907091 in IKZF3 and rs11609 in IQGAP1, which are in strong linkage disequilibrium with the multiple sclerosis associated single nucleotide polymorphisms rs12946510 and rs8042861, respectively." (PMID 27080863, 2016).
primary immunodeficiency (3 papers, 2021 to 2024). "Studies in humans have described IKZF3 missense mutations that compromise the DNA-binding domain and result in primary immunodeficiency and inborn errors of immunity." (PMID 39560988, 2024).
skin cutaneous melanoma (3 papers, 2022 to 2024). "Besides, it had been shown that high expression of IKZF3 usually indicate positive immunological responses and beneficial clinical results of skin cutaneous melanoma." (PMID 39052108, 2024).
B cell deficiency (2 papers, 2021 to 2024). A broad classification of disorders where circulating numbers of B lymphocytes are decreased or ineffective. "The IKZF3 G159R mutation has been associated with B cell deficiency, B cell malignancy, and abnormal T cell differentiation." (PMID 39560988, 2024).
deep vein thrombosis (2 papers, 2023 to 2024). "PLSCR1 and IKZF3 are associated with SLE thrombosis and disease risk." (PMID 39845969, 2024).